AR (androgen receptor)
Diseases named in the same sentence as AR in open-access papers (continued):
Sharing a sentence is not in itself a finding about the gene and the disease.
prostate carcinoma (continued). "It is interesting to note that although DTX3L contains a DTC domain, prostate cancer cells lacking DTX3L still undergo androgen-induced AR degradation." (PMID 40681873, 2025). "The need to individualize therapy in the management of prostate cancer, underpinning the decision to de-escalate treatment or not, still largely depends on the efficacy and duration of hormonal therapy, including androgen receptor and signaling inhibitors." (PMID 40805173, 2025). "R9-AR-PIP also significantly inhibits the growth of AR-positive but not AR-negative prostate cancer cells." (PMID 40391771, 2025). "Through these analyses, we identified dysregulated pathways in AR-negative/-low prostate cancer compared to their AR-positive counterparts." (PMID 39743630, 2025). "In prostate cancer, FOXA1 contributes to AR signaling even in low androgen environments." (PMID 41124032, 2025). "Androgen receptor-negative prostate cancer cells PC-3 and DU145, estrogen-receptor positive breast cancer cells MCF7 and triple-negative breast cancer cells MDA MB 231 that exhibit aggressive behaviors were also sensitive to Super-EBS." (PMID 39781466, 2025). "Enhances AR activity in the absence of androgens, allowing prostate cancer cells to continue growing and develop resistance to treatment." (PMID 40008000, 2025). "Han and colleagues showed that mesenchymal and stem‐like prostate cancer (MSPC) without AR expression is present in treatment‐naïve prostate cancer." (PMID 39651632, 2025). "AR is recognized as an oncogenic driver of TNBC, and AR-positive TNBC patients may benefit from targeted treatments against AR, which have already been implemented in the treatment of prostate cancer." (PMID 39851328, 2025). "Their role in prostate cancer, especially in the case of Elk1, has not been fully uncovered; however, it is known that Elk1 and AR signaling have significant interplay." (PMID 40699751, 2025). "Given the discussions in this review regarding the crosstalk mechanisms between AR and YAP in prostate cancer, we propose that future research could investigate new targeted drugs against YAP and develop more specific therapeutic strategies." (PMID 39963114, 2025). "In addition, it binds to the proximal promoter region of the AR gene; it mainly contributes to the enriched symmetric dimethylation of H4R3 in the same region in prostate cancer and regulates prostate cancer malignancy." (PMID 41154773, 2025). "Similarly, inobrodib (CCS1477) reduces the gene expression driven by AR and C-MYC in prostate cancer." (PMID 40032852, 2025). "Unlike androgen‐sensitive cell lines such as LNCaP, PC3 cells do not express androgen receptors (AR), thereby representing the biological features of advanced‐stage prostate cancer." (PMID 40955046, 2025). "The Enzap trial enrolled patients with metastatic castration-resistant prostate cancer who had not previously received docetaxel or androgen receptor pathway inhibitors and displayed PSMA-positive PET/CT scans with [68Ga]Ga-PSMA-11." (PMID 41300900, 2025). "The absence of AR activity has been shown to lead to reduced levels of cyclin D3 and cyclin A, reduced CDK4 and CDK2 activity, the hypophosphorylation of Rb, and G1 arrest in prostate cancer cells." (PMID 40075623, 2025). "Mechanistically, AR inhibits TDO2 transcription by binding to the TDO2 intron and suppresses GR expression; simultaneously, EZH2-mediated H3K27me3 on the TDO2 transposon (L1PA5) blocks GR binding and TDO2 transcription in androgen-sensitive prostate cancer." (PMID 40759641, 2025). "Moreover, we found that CMV‐infected cells (CMV‐pp71+) expressed higher levels of AR protein than uninfected (CMV pp71−) cells in primary prostate cancer samples (n = 38), suggesting that CMV increases AR levels in prostate cancer cells also in vivo." (PMID 40493023, 2025).
prostate carcinoma (continued). "There is increasing research interest in exploring the molecular and related mechanisms involved in the regulation of prostate cancer that are independent of androgen and AR." (PMID 41347146, 2025). "In prostate cancer, PRPF8 functions as a novel cofactor for the androgen receptor." (PMID 40136404, 2025). "In prostate cancer, lineage alteration can be evaluated by AR activity, unlike in other cancer types, such as lung cancer and melanoma." (PMID 40013333, 2025). "In prostate cancer (PCa), PSAP may play a role in androgen receptor (AR)-dependent carcinogenesis of PCa." (PMID 40801564, 2025). "Further investigation into the therapeutic potential of Bobcat339 on a selection of AR-negative/-low prostate cancer organoid lines revealed a significant inhibition of organoid growth under in vitro condition." (PMID 39743630, 2025). "Although the present study shows that androgen receptor–non-specific (NS) peptides—particularly when combined—reduce prostate cancer cell viability, the absence of detectable effects on androgen receptor or PSA expression highlights mechanistic uncertainties." (PMID 41092058, 2025). "Therefore, it can be concluded that in prostate cancer, YAP not only regulates AR expression but also does so in an IKBKE-dependent manner." (PMID 39963114, 2025). "The relationship between AR alterations and PSMA expression in prostate cancer is complex." (PMID 41124032, 2025). "In this study, we also verified that activation of the Hh signaling pathway does not influence the protein levels of AR but rather promotes prostate cancer progression by enhancing AR activity." (PMID 39785769, 2025). "With the continuous updates in AR research, the study of the AR is no longer limited to prostate cancer." (PMID 40729027, 2025). "Glutamine starvation and inhibition of GLS reduced cell viability of AR-positive as well as AR-negative prostate cancer cells lines, whereby the effect on AR-negative cell lines was more pronounced in comparison to AR-positive prostate cancer cell lines." (PMID 40489535, 2025). "NXP800, but not the inactive chemical control CCT365248, significantly inhibited the growth of all prostate cancer cell lines, independent of their AR status, suggesting that growth inhibition did not occur through AR signaling inhibition alone." (PMID 39787247, 2025). "Moreover, analysis of human prostate cancer datasets from TCGA (Cell, Firehose Legacy, and PanCancer) did not reveal a significant positive correlation between KHDC4 or TRAF2 and androgen receptor expression." (PMID 40560737, 2025). "We found that CPSF1 sustains levels of mRNAs encoding glycolysis regulators, highlighting a vulnerability in advanced prostate cancer that is independent of AR and AR-regulated pathways." (PMID 39847481, 2025). "OCT4, a TF that can form complexes with other TFs (e.g., forkhead box protein A1 (FOXA1), androgen receptor (AR), and nuclear respiratory factor 1 (NRF1)), promotes prostate cancer (PCa) progression through epigenetic alterations and acquires chemotherapy resistance." (PMID 40642070, 2025). "Consistent with this, no AR mutations were detected in the PRC40 and PRC43 organoid cases derived from castration-sensitive prostate cancer patients." (PMID 41463218, 2025).
prostate carcinoma (continued). "Moreover, complex regulatory relationships exist between AR and YAP at various molecular levels, which greatly affect the onset and progression of prostate cancer." (PMID 39963114, 2025). "An emerging challenge in prostate cancer (PCa) treatment is the development of drug cross-resistance, wherein resistance to enzalutamide (ENZ), an androgen receptor signaling inhibitor (ARSI), also confers resistance to subsequent ARSI and docetaxel (DTX) treatments." (PMID 41090793, 2025). "ARI, androgen receptor inhibitors; CTC, circulating tumor cell; EMT, epithelial to mesenchymal transition; mCRPC, metastatic castration‐resistant prostate cancer; NE, neuroendocrine; NEPC, NE prostate cancer; PCa, prostate cancer." (PMID 39840448, 2025). "In the context of prostate cancer, SPOP targets the AR for ubiquitylation and degradation." (PMID 40432836, 2025). "PCSCs (Prostate Cancer Stem Cells) are largely AR-negative, allowing them to evade androgen deprivation therapy and sustain tumor growth through alternative survival pathways." (PMID 40722714, 2025). "Collectively, these observations highlight a shift in the prostate tumor landscape following ADT, moving from AR-positive prostate cancer (PCA1) towards AR-negative/-low prostate cancer (PCA2 and PCA3)." (PMID 39743630, 2025). "Interestingly, AR signaling triggers mTOR‐dependent translation of cyclins D1 and D3 but are suppressed in ADT‐responsive prostate cancer cells when deprived of steroids." (PMID 40007440, 2025). "L14‐8, a small molecule derived from the marketed drug ezetimibe, potently inhibits advanced prostate cancer independent of androgen receptor signaling." (PMID 40536697, 2025). "Despite being one of the leading strategies in current treatment of prostate cancer, Androgen Receptor Pathway Inhibitors are not widely incorporated into CONITEC." (PMID 41092154, 2025). "Altogether, these suggest that prostate cancer cells, regardless of their AR status, do have elevated oxidative stress in comparison to normal prostate epithelial cells." (PMID 41008967, 2025). "Docetaxel is commonly used in advanced prostate cancer to induce cell cycle arrest and apoptosis, targeting rapidly dividing cancer cells regardless of AR status." (PMID 40596459, 2025). "Lastly, recent studies have shown that prostate cancer stem cells, a rare population of cells within the tumor, can survive without needing AR signaling." (PMID 41235005, 2025). "Similarly, in prostate cancer (PCa), PFOS has been shown to disrupt androgen receptor (AR) pathways, promoting abnormal cell growth and progression of PCa." (PMID 41228300, 2025). "In prostate cancer cells, PAD2 citrullination of histone 3 regulates AR signaling." (PMID 41226560, 2025). "HMGB1, whose expression is significantly increased in prostate cancer specimens, has been reported to reactivate and interact with the AR signaling pathway to promote CRPC development in a non-androgen-dependent manner." (PMID 40969278, 2025). "The androgen receptor (AR) is a protumorigenic transcription factor, and aberrant AR signaling drives metastasis and resistance to androgen-deprivation therapy (ADT), a mainstay for prostate cancer treatment." (PMID 39745364, 2025). "BET proteins bolster the functions of key oncogenes by increasing the expression of these drivers, such as c-MYC in leukemia, or by enhancing the transcriptional activities of oncogenic factors, such as Androgen receptor (AR) and Transcription regulator ERG in prostate cancer." (PMID 39851497, 2025). "Cells in lung and prostate cancers resistant to androgen receptor signaling no longer depend on this signal." (PMID 41013839, 2025). "Interestingly, in a mouse model of prostate cancer, overexpression of MYC dampened the androgen receptor transcriptional program via a mechanism involving cofactor redistribution." (PMID 40487451, 2025).
prostate carcinoma (continued). "Androgens play a critical role in maintaining the survival and proliferation of prostate cancer (PCa) by binding to and activating the androgen receptor (AR)." (PMID 40308757, 2025). "Furthermore, GATA2-mediated increased chromatin accessibility facilitated the binding of other TFs, including androgen receptor (AR) and SRY-Box Transcription Factor 9 (Sox9), to CREs in prostate cancer cell lines." (PMID 40516868, 2025). "The androgen receptor binds to regulatory regions of genes involved in the canonical TGFβ signaling pathway, and in prostate cancer, the androgen receptor interacts with androgen response elements (AREs) in the TGFB1 promoter to regulate its transcription." (PMID 40024947, 2025). "Furthermore, the observation that AR bound to the eighth intron of TDO2 in the presence of DHT was also observed in VCaP cells, a different androgen-dependent prostate cancer cell line." (PMID 40759641, 2025). "Similar results were obtained in human prostate cancer Du145 cells, another androgen receptor-negative cell line derived from a PCa metastasis." (PMID 40407591, 2025). "During treatments targeting the androgen receptor, MYCN promotes changes of cancer origin from epithelial to neuroendocrine, which suggests that MYCN can contribute to the NEPC phenotype and drug resistance of prostate cancer." (PMID 39802403, 2025). "Interestingly, melatonin has limited inhibitory effects on androgen-independent prostate cancer cell lines PC-3 or DU145, possibly because the antiproliferative ability of MLT/MT1 depends on the activation of androgen/AR in prostate cancer cells." (PMID 39011396, 2024). "Androgen-receptor-negative, androgen-independent (ARneg-AI) prostate cancer aggressively proliferates and metastasizes, which makes treatment difficult." (PMID 39000112, 2024). "GR activation has been shown to impair AR-negative prostate cancer proliferation through the FOXO3-GAS5 signaling pathway." (PMID 39027480, 2024). "FOXA1 is also an integral part of the AR interactome in prostate cancers but is not required for AR to bind DNA." (PMID 38317241, 2024). "Although the explicit role of GR has not been investigated in AR-negative prostate cancer cells, such as NEPC and DNPC, numerous studies have suggested a clear involvement of GR in these subtypes." (PMID 39027480, 2024). "RORC, AR, LIN28B, IRF9, and IRF3 exert promotive roles in prostate cancer." (PMID 38778150, 2024). "However, prostate cancer generally progresses to castration-resistant prostate cancer (CRPC), which is unresponsive to ADT and androgen receptor signaling-targeted agents (ARSTs) after a few years of ADT." (PMID 38339260, 2024). "We hypothesize that USP54 may influence AR signaling activity in PCa cells by deubiquitinating a protein key to AR signaling activation, However, the specific substrate of USP54 in prostate cancer remains unidentified, necessitating further research." (PMID 38321455, 2024). "It should also be noted that while we have drawn a link between FOXA1, AR, and SEMA3C in prostate cancer, a direct causal relationship cannot be concluded without further studies." (PMID 38528115, 2024). "KDM3A influences the regulation of DNA damage response genes and enhances the chromatin recruitment of c‐Myc in prostate cancer through H3K9me3 demethylation.[10b] Furthermore, targeting KDM3A has the potential to sensitize prostate cancer cells to treatment by inhibiting androgen receptor activity." (PMID 39031630, 2024). "One kinase regulator of AR is cyclin-dependent kinase 9 (CDK9), which phosphorylates AR at serine 81 (pSer81-AR), a modification that enhances AR’s transcriptional activity and prostate cancer cell growth." (PMID 39117800, 2024). "IL-6 mediates AR-independent activation in prostate cancer cells in the absence of androgens, and MAPK involvement is necessary." (PMID 38553750, 2024).
prostate carcinoma (continued). "CRPC-specific AR binding regions are not primarily occupied by typical AR-cooperating factors observed in hormone-sensitive prostate cancer cells but rather by AR-independent transcription factors, such as MYC." (PMID 38698344, 2024). "DIM controls cell growth rates in AR-negative cells, while also targeting the mitochondria inducing apoptosis, which alleviates some of the symptoms of prostate cancer." (PMID 38410780, 2024). "Despite the apparent oncogenic role of GR in AR-negative prostate cancer cells, there are indications of the opposite effect." (PMID 39027480, 2024). "JunD and β-catenin have previously been found to play an oncogenic role in prostate cancer, indicating that menin can increase the tumorigenic potential of AR-negative prostate cancers by increasing the activation of JunD and β-catenin." (PMID 39336822, 2024). "Prostate cancer (PCa) is the most prevalent cancer in men in the Western world, and its primary treatment involves androgen deprivation therapy (ADT) and blockade of androgen receptor (AR) signaling." (PMID 38564048, 2024). "Increasing evidence indicates that the PI3K/Akt/mTOR pathway may directly regulate the expression and activation of AR, which necessitates a dual inhibition of both the AR and PI3K/Akt pathways for a durable control of prostate cancer." (PMID 38254705, 2024). "Consistently with previous reports, the frequency of alterations in AR and HRR genes including BRCA2 and ATM was enriched in mCRPC compared with mCSPC, suggesting that alterations in AR and HRR genes promote treatment resistance to initial ADT-based therapy in prostate cancer." (PMID 39516321, 2024). "As prostate cancer that has progressed to small cell carcinoma lacks AR, there is typically no place in therapy for ADT unless patients are presenting de novo, and the biopsy has a large acinar adenocarcinoma component." (PMID 38903357, 2024). "In our search for a common E3 ligase, we focused on those four ligases that have previously been shown to act on AR, and siRNA depletion experiments clearly showed that only MDM knockdown resulted in increased levels of both AR and TM4SF3 proteins in prostate cancer cells." (PMID 38410785, 2024). "Notably, androgen receptor (AR) signaling governs the expression of EIF5A2 in androgen-dependent cells, promoting prostate cancer metastasis by inducing EMT and elevating EIF5A2 expression." (PMID 38770178, 2024). "However, the putative interplay between AR and any member of NR4A in prostate cancer cells remains to be demonstrated." (PMID 38531859, 2024). "Taken together, these studies confirm that Thio-2 inhibits AR signaling and decreases C-MYC expression to inhibit the growth of prostate cancer cell lines through a mechanism of action that, in these specific studies, appears to be independent of BAG-1 isoform function." (PMID 38412481, 2024). "Given the crucial role of AR prostate cancer, the PARP7-AR axis may be a potential therapeutic strategy for prostate cancer." (PMID 38734665, 2024). "This question arises from observations that CCS1477 has a limited impact on the proliferation of AR-negative prostate cancer cells." (PMID 38564048, 2024). "Using a coculture of C4-2 cells, a metastatic prostate cancer cell line, and human umbilical vein endothelial cells (HU-VEC), the authors show that HUVEC enhanced prostate cancer cell invasion by decreasing androgen receptor (AR) activity in a C-C chemokine ligand type 5 (CCL5)- dependent manner." (PMID 39082334, 2024). "ID2 can activate JAK/STAT signaling pathway as well as FGFR signaling pathway to promote the acquisition of prostate cancer lineage plasticity, which in turn leads to androgen receptor-negative prostate cancer." (PMID 38254880, 2024). "In addition, FOXA1 overexpression increased the proliferative capacity of AR signaling in MDA-MB-453 breast and LNCaP prostate cancer cell lines." (PMID 38317241, 2024).